GAST (gastrin)
Diseases named in the same sentence as GAST in open-access papers (continued):
Sharing a sentence is not in itself a finding about the gene and the disease.
gastritis (continued). "A stress induced rise of cortisol might result in increased prevalence of gastritis and gastric ulcers mediated by an increase of gastrin." (PMID 34765666, 2021). "In the third group, patients with multifocal gastritis whose gastrin-17 level was lower than 10 pmol/l and/or pepsinogen-1 level was lower than 25 μg/l, atrophy in the antral mucosa and corpus ventriculi was confirmed by performing histopathology test of biopsy materials." (PMID 32102507, 2020). "Gastritis affecting the antral mucosa increases the release of gastrin and secretion of acid." (PMID 31487815, 2019). "There were significant differences between both groups regarding liver decompensation (P = 0.001), red color sign over gastric varices (P = 0.0011), prevalence of H. pylori infection (P = 0.0049), histological patterns of gastritis (P = 0.0069), and serum gastrin level (P = 0.0200)." (PMID 30881448, 2019). "Gastroscopy and histology proved a type A gastritis with an increased value of gastrin." (PMID 28057043, 2017). "Further investigation is needed to evaluate if an exercise-induced increase in serum gastrin and cortisol may contribute to gastritis and gastric ulceration in racing sled dogs." (PMID 27112583, 2016). "In early stages of H. pylori gastritis, the bacterium is preferentially localized at the antrum; with continued inflammation, gastrin producing cells are lost in the antrum, probably leading to decrease in acid secretion by the parietal cells and spread of bacteria and inflammation to the corpus." (PMID 27166672, 2016). "If a similar rise in gastrin also exists in racing sled dogs, a possible gastrin-initiated increase in gastric acid may contribute to exercise-induced gastritis and gastric ulcers." (PMID 27112583, 2016). "The other one; H. pylori-induced gastritis can potentially affect the secretion of gastric hormones, including leptin, ghrelin, gastrin, and somatostatin, which could affect insulin sensitivity and glucose homeostasis." (PMID 27148410, 2016). "This gram-negative organism can damage the gastric glands and parietal cells via infiltration, which leads to decreased acid production and secondary hypergastrinemia; however, gastrin levels are usually modest in this form of gastritis, and carcinoids are uncommon in this setting." (PMID 25698559, 2015). "The control of gastrin can prevent H. pylori-induced gastritis." (PMID 25993258, 2015). "Moreover, our data showed that the serum gastrin was significantly lower, and the pepsinogen I/II ratio was significantly higher than before eradication, confirming the improvement of histological gastritis by H. pylori eradication." (PMID 26060821, 2015). "In mild gastritis, inflammation could stimulate the production of PGs by increasing gastrin secretion; while in severe gastritis, the intensive inflammation could reversely reduce the PGs production mainly owing to injured and reduced gastric glands." (PMID 24004680, 2013). "Furthermore, this study revealed a significant reduction in PGE2 levels along with a marked increase in gastrin levels in the restraint stress-induced gastritis group, which may be ascribed to stress-induced corticosterone." (PMID 39861107, 2025). "By applying this gastrin cut-off value to other groups, we demonstrated that the calculated normal gastrin concentration could distinguish patients with gastritis from those with normal stomach with high specificity (92.6%) and a high positive predictive value (97.0%)." (PMID 37210509, 2023). "Moreover, other studies suggested that H-pylori infection and gastritis in the corpus suppress acid secretion and increase gastric juice PH, resulting in hypergastrinemia, and that eradication of H-pylori normalizes acid secretion and serum gastrin levels." (PMID 36674080, 2023).
gastritis (continued). "Subsequently, we conducted a validation study to verify the possibility that the normal serum gastrin concentrations measured from the pathologically-evaluated group could be used as a marker to distinguish gastritis cases from Hp-uninfected cases in the endoscopically-evaluated group." (PMID 37210509, 2023). "If the REG protein is less efficient to induce stimulation of growth of the stem cell compared with the stimulating effect of gastrin on the ECL cell, this could explain that H. pylori gastritis is more prone to predispose to adenocarcinomas with a longer latency." (PMID 34207192, 2021). "However, since gastritis elevates gastrin, the normal upper level became too high." (PMID 32796591, 2020). "Consequently, gastrin-CCKBR level is a vital standard for measuring the severity of gastritis." (PMID 30382864, 2018). "Erosive gastritis and peptic ulcer are the most common upper gastrointestinal disorders and maybe the factors such as an increase in gastrin and stomach acid, increased parathyroid hormone, decreased mucosal resistance and delayed gastric emptying are the main causes." (PMID 29564060, 2018). "In some patients with HP, the organism colonizes the antrum preferentially, resulting in an antrum-dominant gastritis characterized by aggravated GERD symptoms and increased gastrin and acid secretion." (PMID 36968099, 2023). "Gastritis is often seen in CKD patients due to uremia and high gastrin levels, while upper gastrointestinal bleed is mainly attributed to platelet dysfunction secondary to uremia, use of heparin, and increased risk of gastrointestinal ulcers." (PMID 36712748, 2022). "With the increasing concern over the trophic effects of gastrin on the gastric mucosa, the hypergastrinemia in this subgroup of patients could be contributing to the hypertrophy of the gastro-intestinal (GI) tract and occurrence of gastritis frequently noted in ESRD patients." (PMID 25698559, 2015). "Simple and readily available serum markers of gastric inflammation (gastrin and pepsinogen) are indicative of gastritis but are not limited to radiation." (PMID 37788485, 2023). "While this case showed gastritis and negative IF antibodies, gastrin levels were elevated, indicating a mixed picture." (PMID 37664295, 2023). "Using the upper limit of this normal range of serum gastrin concentrations, the sensitivity, specificity, positive predictive value, and negative predictive value for gastritis were 52.8%, 92.6%, 97.0%, and 31.0%, respectively." (PMID 37210509, 2023). "associated gastric diseases by an inhibitory effect on bacterial growth via disruption of cell membrane leading to bacteria lysis, reducing iodoacetamide-induced gastritis by decreasing malondialdehyde (MDA), gastrin, and nitric oxide (NO), and normalizing mucosal glutathione levels." (PMID 35453805, 2022). "In consistence with a study among H. pylori infected subjects we did not observe discriminative ability of PGI, PGII, and gastrin for antral-restricted atrophy or gastritis." (PMID 22066020, 2011). "Proton pump inhibitors (PPIs) are well-known to increase serum gastrin levels, but in some cases, gastrin levels may not serve as a predictive factor for gastritis." (PMID 39518740, 2024). "However, it is noteworthy that some patients with gastritis do not have high serum gastrin concentrations." (PMID 37210509, 2023). "Therefore, even when the gastrin concentration is low, the possibility of gastritis cannot be ruled out." (PMID 37210509, 2023). "Therefore, patients with H. pylori gastritis may not be completely anacidic and accordingly have a less pronounced hypergastrinemia, which also could be due to antral gastritis impairing gastrin release from the G cells." (PMID 34207192, 2021).
Zollinger-Ellison syndrome (34 papers, 2005 to 2025). Zollinger-Ellison syndrome (ZES) is characterized by severe peptic disease (ulcers/esophageal disease) caused by hypergastrinemia secondary to a gastrinoma resulting in increased gastric acid secretion. "ZES (Zollinger-Ellison syndrome) is a rare condition in which gastrin-secreting neuroendocrine tumors cause elevated acid production from gastric parietal cells, thus leading to recurrent peptic ulcers." (PMID 33230760, 2021). "These have focussed mainly on the production of gastrin that can be associated with Zollinger-Ellison syndrome and multiple endocrine neoplasia type 1 (MEN1) syndrome or of somatostatin that may be associated with a unique psammomatous tumor in patients with neurofibromatosis." (PMID 40553402, 2025). "In type 1 multiple endocrine neoplasia (MEN1), esophageal diseases association with excessive gastrin secretion in Zollinger-Ellison syndrome (ZES) sometimes develop." (PMID 28270118, 2017). "It is not considered standard of care to measure duodenal hormones in this setting with the exception of gastrin levels in patients with presumed Zollinger-Ellison syndrome." (PMID 40553402, 2025). "Zollinger-Ellison Syndrome (ZES) is a rare condition characterized by excessive gastric acid secretion due to gastrin-producing neuroendocrine tumors." (PMID 40458720, 2025). "Twelve patients had a clinical diagnosis of Zollinger-Ellison syndrome and had elevated circulating gastrin levels measured." (PMID 40553402, 2025). "Excess gastrin secretion can present as Zollinger-Ellison syndrome, first described in 1955 in two cases of patients with jejunal ulcers who were found to have gastrin hypersecretion." (PMID 37046665, 2023). "In fact, ulcers are one of the main consequences of Zollinger-Ellison syndrome, in which excess of gastrin secretion is produced." (PMID 36496782, 2022). "Known as Zollinger-Ellison syndrome (ZES), peptic ulcer disease can be caused by functioning NET-secreting gastrin because of increased gastric acid secretion." (PMID 35255927, 2022). "Patients with sporadic Zollinger-Ellison syndrome (ZES) rarely develop gastric NETs even though their circulating gastrin levels are over 10-fold above normal for a long period of time." (PMID 32210918, 2020). "A secretin infusion at 1–2 μg/kg will usually produce a marked increase in serum gastrin levels (>200 pg/ml) in patients with Zollinger-Ellison syndrome and is accepted as a confirmatory test only (sensitivity and specificity >90%)." (PMID 25698559, 2015). "Using a delta gastrin of 200 pg/mL, the secretin test has a sensitivity and specificity of 82% and 100% for the diagnosis of Zollinger-Ellison syndrome." (PMID 24213225, 2012). "After localization of gastrin secretion to the head of the pancreas pylorus preserving pancreatico-duodenectomy has been suggested after biochemical diagnosis of Zollinger-Ellison syndrome, with a biochemical cure rate in about two-thirds of the patients." (PMID 24213225, 2012). "The diagnosis of Zollinger-Ellison syndrome is made by demonstrating an increased gastrin concentration in fasting patients in the presence of proven hyperchlorhydria." (PMID 24213225, 2012). "In 20%–30% of these patients the gastrin concentration can be up to five times normal, comparable to the gastrin concentration seen in 60% of Zollinger-Ellison syndrome patients." (PMID 24213225, 2012). "The diagnosis of Zollinger-Ellison syndrome may be further impeded due to technical difficulties with the determination of the correct gastrin concentration." (PMID 24213225, 2012). "In addition, it appears that patients with elevated gastrin levels due to Zollinger-Ellison syndrome have higher markers of colonic proliferation." (PMID 22719803, 2012).
Zollinger-Ellison syndrome (continued). "Thus, while the gastrin concentration in fasting patients with proven hyperchlorhydria is increased, in most Zollinger-Ellison syndrome patients functional testing is recommended due to the large overlap with other pathological conditions with hypergastrinaemia." (PMID 24213225, 2012). "The Zollinger-Ellison syndrome (ZES) occurs as a result of gastrin hypersecretion, from duodenal and panNENs, and may be associated in up to 25% of cases with MEN-1." (PMID 29349087, 2017). "Even though this is a rare disease, it should be considered in patients with Zollinger-Ellison syndrome without evidence of a gastrin producing tumor." (PMID 25698559, 2015). "Cure of Zollinger-Ellison syndrome was defined as a normal gastrin concentration in fasting patients and a negative secretin test." (PMID 24213225, 2012). "Pylorus-preserving pancreatico-duodenectomy may therefore be justified if there is a biochemical diagnosis of Zollinger-Ellison syndrome in MEN-1 and the source of gastrin can be regionalized by preoperative selective arterial secretin injection to the head of the pancreas." (PMID 24213225, 2012).
colon carcinoma (29 papers, 1989 to 2025). "Gastrin as a gastrointestinal hormone has been demonstrated to be a biomarker of cancer risk and a growth factor for colon cancer." (PMID 33806918, 2021). "In addition to regulating the autophagy and apoptosis of colon cancer cells, H. pylori can inhibit gastric acid secretion, indirectly causing the excessive release of gastrin, which leads to the abnormal proliferation of intestinal cells, inducing colon polyps and even colon cancer." (PMID 34895252, 2021). "High GAST (which encodes PG) and MPZL1 transcript levels in primary colon cancer patients is predictive of worse prognosis." (PMID 40753649, 2025). "Another study showed that glycine-extended gastrin stimulates the growth of Human Embryonic cells (HEKs) and human colon cancer cells in vitro." (PMID 38672239, 2024). "One study showed that berberine can significantly reduce gastrin, and the data shed a new light into the anti-colon cancer potential of berberine." (PMID 33806918, 2021). "Incomplete processing and low level of expression of gastrin were observed in five human colon carcinoma cells." (PMID 32210918, 2020). "In contrast, it has been reported that gastrin suppresses the early growth response gene-1/anion exchanger-2/P16/P-ERK signaling pathway to inhibit the growth of colon cancer." (PMID 32485921, 2020). "We then examined the effect of alkaline conditions (pH8 treatment) and/or gastrin (150 pg/mL) on CMT93 mouse colon cancer cells." (PMID 32485921, 2020). "Firstly, we determined the optimum concentration of gastrin which showed maximum stimulatory effect on the proliferation of colon cancer cells by MTT assay." (PMID 28196083, 2017). "Knockdown of CacyBP/SIP retarded the growth of colon cancer cells under both basal and gastrin-treated conditions." (PMID 28196083, 2017). "This is also supported by analysis of the relative abundance of nuclear and cytoplasmic CacyBP/SIP in colon cancer cells by Western blotting before and after 10−8 mol/L gastrin stimulation for 8 h." (PMID 28196083, 2017). "The stimulatory effect of gastrin on the proliferation of colon cancer cells were further demonstrated by cell cycle analysis with flow cytometry." (PMID 28196083, 2017). "We cultured human colon cancer cells, stimulated their proliferation with the carcinogen gastrin and examined the intracellular distribution of CacyBP/SIP." (PMID 28196083, 2017). "This work also provides a rationale for the use of inhibitors of the gastrin in patients with colon cancer." (PMID 28196083, 2017). "CacyBP/SIP promoted the cell proliferation of colon cancer cells under both basal and gastrin stimulated conditions as shown by knockdown studies." (PMID 28196083, 2017). "Our study indicates that gastrin peptides synthesized by colon cancer cells have macrophages as their targets and probably affect the inflammatory infiltrate of the tumor, which in turn affects cancer progression." (PMID 24901518, 2014). "Here we demonstrate that gastrin leads to a dose-dependent increase in colon cancer cell proliferation and tumour growth in vitro and in vivo, and that this increment is progressively reversed by pretreatment with the cyclo-oxygenase-2 inhibitor NS-398." (PMID 12189559, 2002). "Previous research with anti-gastrin antibodies suggested that gastrin could act as colon cancer’s autocrine growth factor." (PMID 38672239, 2024). "As the gastrin gene is expressed in >60% to 80% of human colon cancers, it is reasonable to assume that a sizeable portion of these tumors may strictly depend on the GAST gene products." (PMID 38672239, 2024). "The growth of human colon cancer cells that express high levels of gastrin mRNA may be influenced by the expression of the gastrin (GAST) gene in a physiologically relevant manner." (PMID 38672239, 2024). "It is possible that the nuclear translocation of CacyBP/SIP stimulated by gastrin itself may be playing an important role in colon cancer cells." (PMID 28196083, 2017).